LAD1 (ladinin 1)
Diseases named in the same sentence as LAD1 in open-access papers (continued):
Sharing a sentence is not in itself a finding about the gene and the disease.
gastric cancer (1 paper, 2023). A primary or metastatic malignant neoplasm involving the stomach. "In summary, our study first discovered the malignant tumor-promoting role of LAD1 in gastric cancer and discovered a novel mechanism of LAD1 inhibiting the ubiquitination of Vimentin mediated by MAEA." (PMID 37718450, 2023). "Patients with high LAD1 expression in gastric cancer had worse prognoses than those with low expression." (PMID 37718450, 2023). "According to the results of the current investigation, LAD1 was shown to be strongly expressed in gastric cancer and to be significantly correlated with metastasis." (PMID 37718450, 2023). "However, it is still unclear how and why LAD1 causes gastric cancer (GC)." (PMID 37718450, 2023). "Additionally, we discovered that LAD1 can promote chemoresistance in gastric cancer in vitro and in vivo, LAD1 targeting can promote chemosensitivity, and LAD1 can stabilize Vimentin by reducing MAEA-mediated ubiquitination." (PMID 37718450, 2023).
inflammatory bowel disease (1 paper, 2018). A spectrum of small and large bowel inflammatory diseases of unknown etiology. "IL-23, one member of the IL-12 cytokine family, is crucial in the pathogenesis of psoriasis, experimental autoimmune encephalomyelitis (EAE), collagen-induced arthritis (CIA), inflammatory bowel disease (IBD) and leukocyte adhesion deficiency type 1 (LAD1)." (PMID 29508278, 2018).
leukemia (1 paper, 2009). A malignant (clonal) hematologic disorder, involving hematopoietic stem cells and characterized by the presence of primitive or atypical myeloid or lymphoid cells in the bone marrow and the blood. "Other cell cultures, designated LAD 1 and 2, derived from bone marrow aspirates from a patient with mast cell sarcoma/leukemia, resemble CD34+-derived human mast cells with functional FcεRI and Fcγ RI receptors." (PMID 19379488, 2009).
liver fibrosis (1 paper, 2018). "Lad1 is a part of the basement membrane, which increases around liver vessels in liver fibrosis." (PMID 30526554, 2018).
lymph node metastasis (1 paper, 2025). "Based on the analysis of clinical data, it was found that the positivity rate of LAD1 in LUAD tissues was not significantly different with respect to patient age, gender, tumor location, grade, size, lymph node metastasis, and pleural invasion (P > 0.05)." (PMID 41423496, 2025).
metastatic cancer (1 paper, 2020). A carcinoma which has spread from the original site of growth to another anatomic site. "Extensive interactome studies could help further understand the molecular mechanism of LAD1 in metastatic cancer." (PMID 33267790, 2020). "Furthermore, metastatic cancer tissues tended to display elevated LAD1 staining intensities compared with matched primary cancer tissues." (PMID 33267790, 2020).
metastatic tumors (1 paper, 2022). "In this study, we found that the expression of LAD1 was increased in the tumors of LUAD compared with that in normal tissues, and the expression of LAD1 was further increased in metastatic tumors." (PMID 36613882, 2022).
pancreatic (1 paper, 2023). "According to our research, high LAD1 expression was also associated with a worse prognosis in colorectal, liver, esophageal, and pancreatic malignancies." (PMID 37718450, 2023).
psoriasis (1 paper, 2018). An autoimmune condition characterized by red, well-delineated plaques with silvery scales that are usually on the extensor surfaces and scalp. "It is known that IL-23 is essential for the terminal differentiation of IL-17-producing T effector cells, which were initially shown to be a chief pathogenic cell population in EAE and CIA, human psoriasis and LAD1." (PMID 29508278, 2018). "IL-23 and IL-17 are crucial in the pathogenesis of psoriasis, EAE, CIA, IBD and LAD1." (PMID 29508278, 2018).
renal carcinoma (1 paper, 2019). A carcinoma arising from the epithelium of the renal parenchyma or the renal pelvis. "Finally, LAD1 gene methylation is a potential biomarker for angiogenesis therapy in renal cancer." (PMID 31846472, 2019).
Skin ulcer (1 paper, 2020). A discontinuity of the skin exhibiting complete loss of the epidermis and often portions of the dermis and even subcutaneous fat. "The patients with CD18 expression of more than 30% (LAD1+) presented later in life with skin ulcers being the commonest manifestation." (PMID 33391282, 2020).
WHIM syndrome (1 paper, 2022). "Innate immune cells (e.g., NK cells and neutrophils), which play a role in elimination of virus infection response, are affected in LAD1 deficiency, IL2RG/JAK3 deficiency, and WHIM syndrome." (PMID 35665206, 2022).
tumor (21 papers, 2014 to 2025). "The GSEA results showed that increased LAD1 expression was positively associated with cell proliferation, cancer cell metastasis, and the tumor microenvironment in cancers." (PMID 36613882, 2022). "LAD-1 has been associated with activation of the EGF-to-ERK pathway in tumor cells." (PMID 40789452, 2025). "We also confirmed that LAD1 deficiency remarkably retarded tumor growth in the xenograft model." (PMID 36770773, 2023). "The Ladinin 1 (LAD1) gene was identified recently by our group as a new candidate methylation marker in RCC showing univariate association with adverse clinicopathological parameters such as tumor grade, lymph node metastasis, status of distinct metastasis and advanced disease (unpublished data)." (PMID 24633192, 2014). "To examine the gene expression changes resulting from LAD1 level variations, we analyzed both cancer cell-specific and whole tumor perspectives." (PMID 41423496, 2025). "LAD1 (Ladinin 1) in those pathways has also been found to be significantly correlated with tumor size, lymph metastasis and recurrence events, with higher expression contributing to worse survivals." (PMID 39720074, 2024). "Following that, we established a xenograft tumor model to investigate the role of LAD1 in tumor growth." (PMID 37718450, 2023). "Consistent with the transcriptome data, the expression of LAD1 protein was elevated in the tumor tissue of LUAD." (PMID 36770773, 2023). "The results showed that the volume and weight of the tumor masses in nude mice injected with control cells were almost two times larger than in those with the LAD1-depleted xenografts, indicating that LAD1 is required for LUAD cell growth in vivo." (PMID 36770773, 2023). "When compared to the control, LAD1 knockdown results in reduced tumor growth, including weight and volume." (PMID 37718450, 2023). "Our in vitro and in vivo studies, which are comparable to those on breast and colorectal malignancies provide additional evidence that LAD1 increases cellular invasion and migration, chemoresistance, tumor growth, and lung metastasis in GC." (PMID 37718450, 2023). "Further, we investigated the ability to distinguish tumor tissues from normal ones based on LAD1 gene expression values." (PMID 36770773, 2023). "A Sankey diagram was used to display the detailed routes and patterns across tumor stages, promoter methylation levels, LAD1 mRNA expression, and survival status." (PMID 36770773, 2023). "The levels of LAD1 expression in 535 tumor tissues of LUAD were significantly higher than those in 59 normal tissues (p = 8.2 × 10−26)." (PMID 36770773, 2023). "Upon subdividing the tumor tissues into normal, tumor, and metastatic tissue from the gene chip database, it was found that LAD1 expression was significantly upregulated in the metastatic tissues." (PMID 36613882, 2022). "In our study, the GSEA showed that the transcriptomes of LUAD patients with high levels of LAD1 and B3GNT3 were strongly associated with the tumor microenvironment, suggesting that they cooperated to build the tumor microenvironment." (PMID 36613882, 2022). "Based on public databases, the increased expression of Ladinin 1 (LAD1) was presented in tumor and metastatic sites." (PMID 36613882, 2022). "We further compared the expression level of LAD1 between PCa tumor tissues and normal tissues from TCGA and GTEx project using GEPIA2 databases." (PMID 34516317, 2021). "In the present study, we found that LAD1 was highly expressed in docetaxel-resistant PCa cells, while its expression was significantly suppressed in tumor samples after docetaxel treatment." (PMID 34516317, 2021). "In TCGA-LUAD cohort, LAD1 expression was significantly higher in LUAD tissues in comparison to non-tumor tissues." (PMID 33536022, 2021). "We also compared the expression of LAD1 in PCa tumor tissue and normal tissue, and found that LAD1 expression level in PCa tumor was significantly higher than that in normal tissue." (PMID 34516317, 2021).
tumor (continued). "Therefore, we investigated the impact of LAD1 expression on biological processes and pathways at both the single-cell and whole-tumor levels." (PMID 41423496, 2025). "Our analysis revealed specific expression of LAD1 in cancer cells compared to other cell types.We assessed the impact of altered LAD1 expression on differentially expressed genes (DEGs), biological processes, and signaling pathways at both the single-cell and whole-tumor levels." (PMID 41423496, 2025). "Hypermethylation was found in 8/18 and 10/18 tumor samples for LAD1 and CST6, respectively." (PMID 39051186, 2024). "We speculated that LAD1 was involved in the regulation of the tumor microenvironment and was related to immune cell infiltration." (PMID 36770773, 2023). "Western blot results showed that LAD1 expression was upregulated in most tumor tissues." (PMID 36770773, 2023). "LUAD tumor tissues were also collected to confirm the elevated expression of LAD1 protein." (PMID 36770773, 2023). "LAD1 may promote tumor cell malignancy and play an important role in tumor onset, development, and persistence when present." (PMID 37718450, 2023). "The xenograft model experiment proved that LAD1 knockout remarkably retarded tumor growth in vivo." (PMID 36770773, 2023). "GSVA analysis showed that the overexpression of LAD1 led to the upregulation of a Ras-dependent onco-signature, which may make tumor cells “K-Ras addicted”." (PMID 36770773, 2023). "To verify whether LAD1 was involved in modulating LUAD tumor growth in vivo, we implanted wild-type and LAD1-knockout PC-9 cells subcutaneously in Balb/c nude mice." (PMID 36770773, 2023). "Furthermore, the protein expression of LAD1 in paired normal and tumor tissues from the eight in-house patients was inspected with immunohistochemistry staining, and all eight of the samples overexpressed LAD1 proteins in their tumor parts." (PMID 36613882, 2022). "Similarly, the expression of LAD1 was also profoundly upregulated in the tumor parts of pathological stages I to II LUAD from the GSE31210 database." (PMID 36613882, 2022). "Finally, high expression of LAD1 in PCa tissue was also correlated with the expression level of genes involving in tumor cell proliferation and invasive behaviors." (PMID 34516317, 2021). "In addition, a higher expression level of LAD1 was observed in PCa tumor samples than BPH (benign prostate hyperplasia) samples (164 PCa samples vs 39 BPH samples, GSE134051)." (PMID 34516317, 2021). "TMEM108 and C3orf47 were positively correlated with tumor grade and eight genes, including LAD1, TIF1, FGF11, carbonic anhydrase 12 (CA12), G protein subunit α15 (GNA15), junction plakoglobin (JUP), plakophilin 1 (PKP1) and PPARD, were negatively correlated with the tumor grade of ESCC patients." (PMID 28904855, 2017). "LAD1 may be involved in LUAD progression through its effects on tumor cell migration and invasion." (PMID 41423496, 2025). "The high expression of LAD1 could also be detected in residual tumor tissues after treatment." (PMID 36770773, 2023). "The upregulation of SINGH_KRAS_DEPENDENCY_SIGNATURE was the only activated oncogenic signature in the LAD1 high-expression group, suggesting that the overexpression of LAD1 may facilitate the activation of K-Ras, resulting in the so-called “K-Ras addiction” of tumor cells." (PMID 36770773, 2023). "LAD1 was significantly upregulated in LUAD and several other tumor types compared to normal tissues." (PMID 41423496, 2025). "Previously, we described a prognostic model comprising five DNA methylation markers (i.e., GREM1, GATA5, LAD1, NEFH, and NEURL) in combination with clinicopathological characteristics (i.e., age at diagnosis, sex, Fuhrman grade, tumor size, and TNM stage)." (PMID 40820938, 2025). "In summary, LAD1 expression is increased in LUAD tissues, and knocking down LAD1 can significantly inhibit the migration and invasion of LUAD tumor cells." (PMID 41423496, 2025).
tumor (continued). "Firstly, we analyzed the aberrant expression of LAD1 in LUAD and its correlation with patient survival, tumor immune infiltration, and the activation of cancer signaling pathways." (PMID 36770773, 2023). "Along with LAD1 mRNA expression, LAD1 protein expression levels in the primary LUAD tumor were significantly increased in the CPTAC cohort (p-value < 0.001)." (PMID 36613882, 2022). "To narrow down the candidate genes, we utilized survival analysis, tumor grades, a correlation study, and cross-analysis, B3GNT3 was highly correlated with LAD1." (PMID 36613882, 2022). "Among overlapping downregulated genes in BA patients versus WA patients in both tumor and TAS are tumor suppressors p16 (CDKN2A), filamin A (FLNA) and ladinin 1 (LAD1)." (PMID 34316327, 2021). "Transcriptome analysis on PCa biopsy tumor samples before and after combined therapy of docetaxel and ADT further supports the downregulation of LAD1 after docetaxel treatment." (PMID 34516317, 2021). "Primary tumor tissues from 18 patients receiving targeted therapy were examined retrospectively using quantitative methylation-specific PCR analysis of CST6, LAD1, hsa-miR-124-3, and hsa-miR-9-1 CpG islands." (PMID 24633192, 2014). "Previously, we developed a prognostic biomarker model containing five DNA methylation markers (GREM1, GATA5, LAD1, NEFH, and NEURL) in combination with clinicopathological characteristics including age at diagnosis, sex, Fuhrman grade, tumor size, and TNM 3rd edition staging system." (PMID 40820938, 2025). "Functionally, LAD1 promotes cellular invasion, migration, proliferation, and chemoresistance in vivo and in vitro in the subcutaneous patient-and cell-derived xenograft (PDX and CDX) tumor models." (PMID 37718450, 2023). "Furthermore, the relationship between LAD1 expression and K-Ras and EGF signaling activation, tumor cell proliferation, migration, and colony formation was studied by gene knockout/knockout methods." (PMID 36770773, 2023). "Methylation of GREM1, GATA5, LAD1, NEFH, NEURL, and SFRP1 was associated with poor ccRCC-specific survival, independent of age, sex, tumor size, TNM stage or tumor grade." (PMID 33947447, 2021). "This analysis consistently showed the upregulation of LAD1 in PCa tumor samples (492 PCa tissues vs 152 normal tissues, TCGA and GTEx data)." (PMID 34516317, 2021). "Proteomic profiling of laryngeal cancer tissues showed that LAD1 protein is enriched specifically in metastatic tissues but not in paired adjacent normal tissues and primary tumor tissues." (PMID 33267790, 2020). "Transmembrane protein 108 (TMEM108), C3orf47 and coenzyme Q8A (CABC1) were the top three genes positively correlated with tumor grade, whereas ladinin 1 (LAD1), TIAF1 and FGF11 were the top three genes negatively correlated with the tumor grade of ESCC patients." (PMID 28904855, 2017). "First, the potential LAD1 and CST6 DNA methylation-based markers were measured in tumor cells, which directly exhibit tumor characteristics that may represent drivers of resistance and biological aggressiveness." (PMID 24633192, 2014). "Therefore, we used the CPTAC database to analyze differences in LAD1 phosphorylation levels between primary tumor tissues and normal tissues." (PMID 36770773, 2023).
cancer (15 papers, 2016 to 2025). A tumor composed of atypical neoplastic, often pleomorphic cells that invade other tissues. "Through correlation analysis, we observed that LAD1 expression levels were statistically associated with several cancer-related genes, including SFTPB, S100A6, CEACAM6, KRT19, S100A10, ANXA2, S100A11, and CAPN2." (PMID 41423496, 2025). "Our study focused on LAD1, a basement membrane filament protein that has been implicated in tumorigenesis in various cancers." (PMID 41423496, 2025). "The high expression of LAD1 in cancer cells, its associations with LUAD-related genes, and its links to biological processes and pathways suggest its potential biological relevance and that it merits further investigation." (PMID 41423496, 2025). "The high expression of LAD1 in cancer cells led us to explore its potential associations with genes previously implicated in LUAD tumorigenesis." (PMID 41423496, 2025). "To dissect the functional role of LAD1 in cancer progression, we identified the association of LAD1 with cancers using two enrichment analyses, GSEA and GSVA." (PMID 36613882, 2022). "These bioinformatic analysis reports suggest that upregulation of LAD1 is strongly associated with cancer progression and poor clinical outcomes, mainly through a metabolic pathway." (PMID 36613882, 2022). "LAD1 is associated with progressive behaviors and is linked to poor outcomes in various cancer types." (PMID 36613882, 2022). "Nonetheless, LAD1 loss mediated defects in invadopodia activity to degrade the extracellular matrix and consequently impaired the invasion and migration of cancer cells." (PMID 33267790, 2020). "LAD1, a novel protein, has been implicated in the development of cancer." (PMID 37718450, 2023). "Furthermore, the pan-cancer analysis revealed that LAD1 is associated with a worse outcome and accelerates carcinogenesis." (PMID 37718450, 2023). "LAD1 has been implicated in the progression of different cancers." (PMID 34516317, 2021). "Moreover, LAD1 has been implicated in the progression of different cancers." (PMID 33267790, 2020). "Pathway analysis indicated enhanced cancer-related and HIF-1 signaling pathways and suppressed phagosome and antigen processing and presentation pathways in cancer cells with high LAD1 expressions." (PMID 41423496, 2025). "Our findings revealed that LAD1 was highly expressed in cancer cells, highlighting its potential significance in LUAD." (PMID 41423496, 2025). "We analyzed scRNA-seq data from 10 LUAD patients and identified nine cell subgroups, with LAD1 specifically expressed in cancer cells." (PMID 41423496, 2025). "Focusing on the cancer cell subgroups in the scRNA-seq data, we determined the differentially expressed genes (DEGs) between cancer cells with high and low LAD1 expression and visualized the top altered DEGs using a heatmap." (PMID 41423496, 2025). "Pan-cancer analyses demonstrated LAD1 as an independent prognostic factor for overall survival in LUAD." (PMID 41423496, 2025). "The results showed that the positive rate of LAD1 in LUAD cancer tissues was significantly higher than that in adjacent tissues (P < 0.001)." (PMID 41423496, 2025). "In terms of cancers, LAD1 showed high expression in bowel, biliary tract, prostate, and other cancer types." (PMID 41423496, 2025). "Using the “FindMarkers” function, we discovered that LAD1 was specifically expressed in the cancer cell subgroup, with significantly higher expression compared to other cell types, including normal epithelial cells." (PMID 41423496, 2025). "Single-cell analysis showed that FBLN5 and LAD1 were overexpressed in fibroblasts and cancer cells, respectively, compared to normal cells." (PMID 37325048, 2023). "To evaluate the association between LAD1 expression and prognosis in LUAD, we first used gene-chip data by categorizing cancer cases into high- and low-expression groups." (PMID 36770773, 2023).